GLI1 (GLI family zinc finger 1)
Diseases named in the same sentence as GLI1 in open-access papers (continued):
Sharing a sentence is not in itself a finding about the gene and the disease.
cancer (continued). "In addition, the phosphorylation of aPKC was significantly correlated with the expression of Gli1, PARD3 and Sox2 (R > 0.4), emphasizing the important role of aPKC in mediating PARD3, SHH signalling and cancer stemness." (PMID 38317186, 2024). "Arsenic trioxide (ATO), a Gli1/2 suppressor, is the first FDA approved drug that targeted the Hh pathway to treat acute promyelocytic leukemia ATO and currently undergoing preclinical testing for a variety of cancers, including prostate and colon cancer." (PMID 37305676, 2023). "In cancers, GLI1 can also be activated in a non-canonical way by the “oncogenic load” of the cancer cell." (PMID 36900263, 2023). "Direct comparison between KIRC tumor tissues and morphologically unchanged (control) kidney samples revealed a lack of statistical difference between the expression of SHH and approximately 1.25- and 1.5 higher immunoreactivity of GLI1 and VEGFA proteins, respectively, in cancer cells." (PMID 37964226, 2023). "Activated Gli1 triggers the transcription of a panel of genes, including Bcl2, c-Myc, Nanog, FOXS1, and PDL1, and promotes the proliferation, survival, invasion, and migration of cancer cells." (PMID 38097536, 2023). "The lack of SNF5 protein, typically involved in limiting Gli1 expression, leads to Gli1 overexpression and drives the growth of cancer cells." (PMID 37815662, 2023). "Cancers with this type of activation show high levels of ligands, with no expression of the pathway’s target genes (GLI1, GLI2, and PTCH1), which are only detectable in stromal cells." (PMID 36765685, 2023). "Key roles of CD155-CD226 and CD155-CD96 checkpoints in cancer cell/CD8+ T cell interactionPhosphorylation of VAV1 in CD8+ T cells via BCL9 suppression, mediating Wnt transcriptionUpregulation of GLI1 and PATCH expression in promoting CD155 expression in cancer cells." (PMID 36032085, 2022). "Non-canonical activation of GLI1 seems to account for the low therapeutic efficacy and resistance of clinically available Smo inhibitors (vismodegib and sonidegib) in cancer treatment." (PMID 36046646, 2022). "As a mechanism of crosstalk, potentially relevant to cancer and developmental signaling, ERK2 MAP kinase phosphorylates the Hedgehog-pathway transcription factor GLI1 on three sites, promoting release of the negative regulator SUFU and the consequent activation of GLI1." (PMID 35831023, 2022). "Although GLI1 plays a key role in canonically activated Hh cancers, non-canonical oncogenic activation (CMYC, RAS/RAF, TGFβ, etc) is critical to address as well." (PMID 34113570, 2021). "IL-6 can also be produced directly by cancer cells, such as in basal cell carcinoma (nonmelanoma skin cancer) where IL-6 is secreted through the HH/ GLI1 pathway via STAT3 activating IL-6." (PMID 33691728, 2021). "In the scope of oncogenesis, GLI1 activation is particularly dominant in subsets of a number of cancer types because parallel non-canonical pathways outside of hedgehog signaling influence GLI1 function." (PMID 34113570, 2021). "As would be expected, this isoform of GLI1 functions as a constitutively active protein, with activity comparable to full-length GLI1 (GLI1FL) but surprisingly does not show a preferential expression in cancer tissues." (PMID 34113570, 2021). "HH/GLI1 signaling regulates immune checkpoint modulators such as PD1, CTLA-4, TIM3, LAG3, TIGIT, and IL-10 in exhausted T cells as well as PD-L1/2, CD80/86, OX40L, CD137L, IDO, and CCL22 in cancer cells." (PMID 34831357, 2021). "Therefore, we demonstrate that oncogenic upregulation of GLI1 amplifies NBS1 expression, resulting in an enhanced DDR in a subset of cancer cells, in turn promoting survival in high genotoxic stress environments." (PMID 32185127, 2020). "GLI1 was identified as a novel regulator of NBS1 and discovered that by knocking down GLI1 levels in vitro, diminished NBS1 expression, increased DNA damage/apoptosis, and re-sensitization of 5-FU resistant cancer to treatment was observed." (PMID 32185127, 2020).
cancer (continued). "The divergence between the prognostic value of GLI1/2 expression and that of HH ligands indicates that there is no sensible justification for targeting HH for cancer treatment if GLI1 expression is used as a prognostic variable." (PMID 32879407, 2020). "Additionally, in a pan cancer analysis, a positive correlation between TGF-β-related gene expression and GLI1 and GLI2 expression was observed." (PMID 32245491, 2020). "Our broad pan-cancer analysis herein indicates that GLI1/2 functions parallel or match those of TGF-β ligands, not HH, as identified both in linear models of oncogenic functions and in prognostic analyses of tumors." (PMID 32879407, 2020). "Moreover, the use of GLI1 inhibitors, or knocking down GLI1 by using siRNA or GLI1 CRISPR/Cas9, was studied to determine the role of GLI1 in regulating cancer stem cells through downregulation of OCT4 and Nanog by GLI1 silencing." (PMID 31614431, 2019). "Activated GLI1 through the non-classic Integrin αvβ3/ERK1/2 pathway to initiate the transcription of downstream related target genes in order to maintain cancer stem cell-like phenotype of MCAs." (PMID 31366904, 2019). "On the other hand, the expression of Gli1 can be stimulated non-canonically via cross-talk with other signaling pathways, which often happens in pathological states such as cancer." (PMID 30754706, 2019). "This study identified a stronger expression of SMO and Gli1 in borderline and malignant tumor tissues compared with normal ovarian epithelial or benign tumor tissues." (PMID 31261739, 2019). "Previous research has demonstrated that GLI1 transcriptionally regulates several transmembrane efflux transporters, such as MDR1/ABCB1, MRP1, LRP, and BCRP/ABCG2, which mediate chemotherapy resistance in several cancers." (PMID 29930746, 2018). "The mTOR target S6 (a serine/threonine kinase) has previously been shown to activate GLI1 in multiple cancer types, independent of SMO, indicating a crosstalk between the PI3K/AKT/mTOR- and Hh pathways." (PMID 28789624, 2017). "Genetic alterations, including loss of PTCH function, constitutively active SMO, and amplification of GLI1/GLI2 have been reported to activate downstream Hedgehog signaling independent of ligands in various cancers." (PMID 26936993, 2016). "Moreover, numerous examples of cancer-relevant genes affected at the splicing level (e.g. ANXA7, GLI1, MAX, KLF6) have been reported in GBM." (PMID 27287018, 2016). "Compared to parental cancer cells, spheroid cells overexpressed CD44, CD133, Oct4, Nanog, β-catenin, SOX2, Gli1 and p-ERK, which provided evidence for the existence of CSCs and suggested some of these markers might be used to identify gastric CSCs." (PMID 26769843, 2016). "Furthermore, dysregulation of Gli1, a key transcription factor in the Hh pathway, has also been shown to affect EMT in cancer cell lines and lymphatic metastasis, including GC." (PMID 27836001, 2016). "Nevertheless, stratified by cancer type and subcellular localization, cytoplasmic Gli1 expression and Gli1 positivity in intracranial tumors was not correlated to poorer 3-year and 5-year prognosis." (PMID 26899488, 2016). "A recent study has shown that the mTORC1 substrate, S6K1, directly regulates hedgehog signalling in cancer cells by interacting with and phosphorylating Gli1, but not Gli2 via a SMO-independent mechanism." (PMID 27039827, 2016). "The level of Gli1 was significantly higher in cancer tissues than adjacent normal tissues, similar with the IHC results." (PMID 27863385, 2016). "Several former researches showed that the Wnt, PI3K/AKT, and SHH/Gli1 pathways may be activated in CD44 positive and/or CD133 positive cancer cells." (PMID 26769843, 2016). "We asked whether USP21 regulates the stability of Gli1 and turned to CRISPR-CAS9 technology to knockout USP21 in HEK293T cells, which, like many cancer cells, show autonomous expression of Gli1." (PMID 27621083, 2016).
cancer (continued). "Studies have shown that mTOR signalling can activate Gli1 expression through canonical and non-canonical pathway in human cancer cells 14,19." (PMID 26218750, 2015). "Early studies of GLI1 in DNA repair and cancer focused on the canonical HH signaling pathway; however, recently a non-canonical pathway for activation of GLI1 by oncogenic proteins has been elucidated." (PMID 26633513, 2015). "Both GLI1 and GLI2 are oncogenes, constitutively activated in many types of human cancers." (PMID 24962990, 2014). "Gli1 and S100A4 proteins localized almost exclusively to the neoplastic cells beside weakly positive staining of Shh in the islet cells and the chronic pancreatitic duct complex occasionally being seen in pancreatic tissues apart from cancer." (PMID 25072505, 2014). "It is also to be noted that in each cancer scenario, there was another activation link from GLI2 which could up regulate GLI1." (PMID 23935937, 2013). "Aberrant activation of HH signaling in human cancers could result from genetic alterations in pathway components, including PTCH1, SMO, SUFU and GLI1." (PMID 23826113, 2013). "Since the GLI proteins are transcription factors, we hypothesized that GLI1 and GLI2 transcriptionally regulate hTERT expression in cancer cells." (PMID 24086482, 2013). "The proliferation of cancer stem cells could be inhibited by a blockade of the Hedgehog pathway due to the deletion of SMO or (and) Gli1." (PMID 24331293, 2013). "Nonetheless, it is notable that the only HPV-positive sample with GLI1 overexpressed above levels observed for normal samples was from a smoker with cancer in the larynx, not typical of the clinical characteristics of HPV-positive HNSCC." (PMID 24223768, 2013). "Furthermore, Expression of BMI-1, GLI1, GLI2, GLI3 and a list of cancer related microRNAs were also quantified." (PMID 21826251, 2011). "Although HH/GLI1 signalling modulates CSC biology in various tissues, defining itsrole in PCa is complicated by the fact that cancer-initiating cells may stem fromAR− (basal) or AR+ (intermediate/luminal)populations." (PMID 21633508, 2011). "Consequently, GLI1 and its upstream positive regulator Smoothened (SMO) are important targets of anti-cancer therapy and several SMO-targeted small molecule inhibitors are being evaluated clinically." (PMID 21119888, 2010). "Cyclopamine administration attenuated Hh signaling in the stroma rather than in the cancer cells as reflected by decreased expression of full length Gli2 protein and Gli1 mRNA specifically in the compartment." (PMID 20098680, 2010). "GLI1 and HIP1 expression was detected in 9 of 34 (~26%) and 7 of 34 (~21%) cancers respectively." (PMID 19943941, 2009). "This noncanonical activation of GLI1 occurs in several cancers, including PDAC." (PMID 41314543, 2025). "Since both canonical and non-canonical routes culminate with the activation of the GLI1 transcriptional program, GLI1 inhibition could be useful to prevent chemoresistance in cancer cells." (PMID 36900263, 2023). "Combinatorial inhibition of upstream proteins that drive GLI1/2 and inhibition of GLI1/2 may prove to be a potent therapeutic strategy for cancers with noncanonical activation of GLI1/2." (PMID 36010600, 2022). "Elevated levels of GLI1 in cancer are often driven by non-canonical pathways." (PMID 34113570, 2021). "GLI1 protein levels were also reduced in a dose-dependent manner upon treatment with IBET-151, and this observation is consistent with previous studies showing IBET-151 attenuating the activity of a number of genes important to the proliferation and survival of cancer cells, including GLI1." (PMID 32913560, 2020). "However, GANT61, which inhibits GLI1 and GLI2 activity, could reduce the proliferation of cancer stem cells in culture." (PMID 31979397, 2020).
cancer (continued). "Mechanistically, GLI1 is phosphorylated and activated in a SMO-independent manner by MAPK-ERK1/2 signaling, that can be induced by KRAS or through stimulation of Neuropilin 2 receptor by its ligand VEGFA, secreted by cancer cells in an autocrine loop or by stromal cells in a paracrine manner." (PMID 31244888, 2019). "Moreover, Hh ligands produced by cancer cells are also proposed to modulate EC function directly: Shh is highly expressed in human tongue oral squamous cell carcinoma (OSCC) whereas Ptch1, Gli1 and Gli2 proteins are expressed in the microvascular cells in the tumor invasive front." (PMID 31238510, 2019). "This phenomenon suggests that there may be negative feedback between FOXS1 and GLI1 in human cancers that needs to be further studied." (PMID 30918291, 2019). "It is tempting to speculate that this may be because Gli1 is less sensitive to inhibitory posttranslational modifications, such as PKA phosphorylation, or because its expression is more flexible, enabling cancer cells to more easily hijack it to promote their survival and proliferation." (PMID 30754706, 2019). "The authors show also a positive correlation between the expression of MEP50/PRMT5 and that of GLI1 target genes in several HH-dependent cancers, and demonstrate that targeting of MEP50/PRMT5 complex may synergize with SMO inhibitors in suppressing cancer cell proliferation and invasion." (PMID 31244888, 2019). "However, no significant increase in Gli1 or Gli3 expression was observed in the whole collection of cancer tissues, possibly because of the extensive individual complexity." (PMID 29722127, 2018). "Thus, identification of the negative GLI1 regulators to control GLI1 protein level and activity is critical for inhibition of cancer cell growth." (PMID 28562331, 2017). "Importantly, overexpression of GLI1 and/or GLI2 could be correlated with a poor prognosis for the patients in several cancer entities." (PMID 28418873, 2017). "In light of these findings we hypothesized that targeting DYRK1B may represent a novel strategy to inhibit oncogenic GLI1 activity in cancer cells with non-canonical, SMO-independent GLI1 activation." (PMID 26784250, 2016). "Additionally, 12 T cells also showed increased expression of the stemness genes Sox2, Oct4 and Nanog as well as several developmental genes known to be deregulated in cancer stem cells, such as SHH, Notch1, Gli1, and Jagged gene expression and protein expression." (PMID 26597727, 2015). "The results suggested that the relative luciferase activity in 6 Gy irradiated cancer cells was significantly higher than that in non-irradiated cancer cells (P<0.01), indicating that Gli1 transcriptional factor activity was increased in 6 Gy irradiated cancer cells." (PMID 23762282, 2013). "We observed that although the activation pathways (broken red arrows)from SMO to GLI1 and GLI2 via STK36 protein were blocked by the effect of SMO inhibitor in each cancer scenario, HFU could also activate GLI1 and GLI2 in each cancer scenario (solid green arrows)." (PMID 23935937, 2013). "However, the role of the Hh-GLI1 signaling pathway in cancer metabolism has not been well studied." (PMID 36046646, 2022). "In CAPAN-1 cells, which produce Shh ligand but express very little Gli1 mRNA, treatment with Oxy186, HPI-1, and Gant61 resulted in a significant inhibition of Shh expression, indicating that Shh ligand expression may also be influenced by Hh signaling in some cancer cells." (PMID 31137846, 2019). "Although there are currently no GLI inhibitors in clinical trials for CML, GANT61 is a dual GLI1/2 inhibitor that has demonstrated effectiveness in multiple cancer models." (PMID 36986819, 2023).
cancer (continued). "Studies in multiple organ systems and cancers have also demonstrated that GLI transcription factors activate other Hh pathway components such as Ptch1, Smo, Gli1, Gli2, and Gli3, leading to positive and negative feedback of the Hh signaling pathway." (PMID 37675356, 2023). "In addition, one study showed that transcriptional factor GLI1 aggravated cancer cell migration and cancer stem cell (CSC)-like characteristics, while berberine could downregulate CSC-like characteristics and reverse EMT by inhibiting chemotherapy-activated GLI1/BMI1 signaling pathway." (PMID 35889396, 2022). "The protein levels of Gli1, Ptch1, and SMO were examined after itraconazole treatment, and signals decayed after peak in endothelial cells, which was not shown in cancer cell." (PMID 28747628, 2017). "In the same manner, the histopathological progression of cancer has a markedly higher expression of GLI-1, unlike early disease stages, which show a predominance of GLI-3 expression over GLI-1." (PMID 28948003, 2017). "We further detected the expression of some reported stemness-related genes in HCC and CRC stem cells including CTNNB1, HES1, SMAD4, GLI1, STAT3 and BMI122, 23, 24, 25 in the cancer cell lines with or without PS341 treatment." (PMID 26915315, 2016). "For example, multifunctional cytokine TGFβ has been shown to elevate the expression of GLI1 independent of HH mediated signaling, but in a GLI2 dependent manner in different types of normal and cancer cells." (PMID 26633513, 2015). "HIP1 expression was only detected in 2 specimens which expressed PTCH1 or Gli1, indicating that HIP1 is not highly expressed in ovarian tissues or is silenced in cancers as reported in other studies." (PMID 19943941, 2009). "Cancer patients with Hedgehog pathway overactivation develop drug resistance to FDA-approved SMO inhibitors due to the compensatory SMO-independent, non-canonical activation of GLI1/2." (PMID 37950038, 2024). "However, ectopic expression of GLI-1 increased KRAS promoter activity in cancer cells without KRASG12C-inhibitor treatment, suggesting that GLI-1 plays a role in enhancing KRAS-promotor activity." (PMID 38225225, 2024). "In addition, we demonstrate that KRASG12C inhibitors decreased Aurora kinase A (AURKA) levels in cancer cells, and inhibition of AURKA using siRNA or inhibitors led to increased expression levels of GLI-1 and KRAS even in the absence of KRAS inhibitor." (PMID 38225225, 2024). "Since non-canonical signaling may result in oncogenic expression of GLI1, inhibiting upstream molecules like SMO may not be useful for cancer therapy." (PMID 31085420, 2019). "Indeed, western blot quantification of Gli1 protein expression, a downstream effector in the Hh pathway, showed higher Gli1 protein levels in pure CSCs (IENS and G7), compared with non-stem cancer cells (PANC1, SKOV3 and GL261)." (PMID 28322108, 2017). "However, the GLI1 inhibitor blocked the Hh pathway more effectively than the SMO inhibitor, likely because cancer cells exhibit “non-canonical” activation of the Hh pathway, which is caused by alternative signaling pathways (ErbB receptors, NF-κB, Wnt, and Notch)." (PMID 26843616, 2016).